FOXD1 (forkhead box D1)
Diseases named in the same sentence as FOXD1 in open-access papers (continued):
Sharing a sentence is not in itself a finding about the gene and the disease.
glioma (continued). "In this study, based on bioinformatics analysis, we hypothesized that SNHG18 could promote glioma progression via modulating microRNA-338-5p (miR-338-5p) and forkhead box D1 (FOXD1)." (PMID 34937497, 2022). "Previous studies illustrated that FOXD1 can regulate the stemness of mesenchymal glioma stem cells." (PMID 34348789, 2021). "Previous studies have shown that FOXD1 also participates in the development of various cancers, including liver cancer, cervical cancer, pancreatic cancer, breast cancer, and glioma." (PMID 34348789, 2021). "In glioma, FOXD1 upregulates ALDH1A3 to promote stemness properties." (PMID 31795213, 2019). "In addition, qRT-PCR showed that FOXD1 mRNA expression was up-regulated in glioma tissues." (PMID 34937497, 2022). "The overexpression of FOXD1 promotes DKK1 transcription by activating its promoter, thereby promoting glioma cell migration, invasion, and VM." (PMID 37906341, 2023). "In this study, we found that the expression levels of UBA2, RALY, FOXD1, and DKK1 were significantly increased in glioma cells and tissues and were negatively correlated with the overall survival time in glioma patients." (PMID 37906341, 2023). "Silencing of FOXD1 downregulated the expression of DKK1 by inhibiting its transcription and, thus, decreased migration, invasion, and vasculogenic mimicry in glioma cells." (PMID 37906341, 2023). "Interactions among UBA2, RALY, FOXD1, and DKK1 play an important role in regulating migration, invasion, and vasculogenic mimicry in glioma cells." (PMID 37906341, 2023). "Another study reports that silencing FOXD1 represses MEK-2, ERK-1, Bcl-2, DAF, and PCNA expression levels and increases Bax expression, thus repressing glioma cells’ proliferation and metastasis." (PMID 34937497, 2022). "SNHG18 directly targeted the miR-338-5p/FOXD1 axis, and miR-338-5p inhibition weakened the inhibiting effects of SNHG18 knockdown on proliferation, migration and invasion of glioma cells." (PMID 34937497, 2022). "In addition, we profiled the expression of UBA2, RALY, FOXD1, and DKK1 and explored the probable interaction mechanism among these molecules in the regulation of vasculogenic mimicry (VM) in glioma." (PMID 37906341, 2023). "In accordance with its oncogenic role in these studies, the GEPIA database revealed a negative correlation between FOXD1 expression and the overall survival of patients with glioma." (PMID 37906341, 2023). "Moreover, the overexpression of FOXD1 rescued the suppression of migration, invasion, and VM induced by RALY knockdown in glioma cells." (PMID 37906341, 2023). "In addition, we found that the inhibition of UBA2, RALY, FOXD1, and DKK1 inhibited glioma cell migration, invasion, and vasculogenic mimicry." (PMID 37906341, 2023). "UBA2/RALY/FOXD1/DKK1 axis may play crucial roles in regulating VM in glioma, which may contribute to the development of potential strategies for the treatment of gliomas." (PMID 37906341, 2023). "Furthermore, overexpression of FOXD1 rescued the suppression of migration, invasion, and VM induced by RALY knockdown in glioma cells." (PMID 37906341, 2023). "Pearson’s correlation analysis manifested that FOXD1 mRNA expression was in negative correlation with miR-338-5p mimics in glioma samples; FOXD1 mRNA was positively correlated with SNHG18 expression." (PMID 34937497, 2022). "However, an in-depth mechanism of the functional role of FOXD1 and DKK1 in glioma VM remains unknown." (PMID 37906341, 2023). "The inhibitor of UBA2, RALY, FOXD1, and DKK1 may serve as the therapeutic target in glioma." (PMID 37906341, 2023).
melanoma (15 papers, 2015 to 2024). A malignant, usually aggressive tumor composed of atypical, neoplastic melanocytes. "The overall survival rate of melanoma cells was reduced by high FOXD1 expression, which was positively associated with resistance to BRAFi or a combination of BRAFi and MEKi." (PMID 39494294, 2024). "Other mechanisms of MMP-9 over-expression in melanoma are mediated by neural crest associated genes, i.e., FOXD1, via the RAC1B pathway." (PMID 32392801, 2020). "Of note, the invasive/MITF-low signature is also associated with high expression of the NC-associated gene FOXD1 which was recently described to play a key role in melanoma migration and invasion via RAC1b regulation." (PMID 31118886, 2019). "Overexpression of FOXD1 using miniCoopR accelerated melanoma onset—the first demonstration that FOXD1 is oncogenic in any lineage—thereby highlighting the importance of FOXD1 silencing in melanoma." (PMID 35223844, 2022). "Another study showed that upregulated FOXD1 contributed to melanoma cells’ resistance to vemurafenib via the recruited expression of connective tissue growth factor." (PMID 35886008, 2022). "Functional work on FOXD1 in cutaneous melanoma elucidated its capability to induce the expression of the tumor-specific isoform Rac Family Small GTPase 1B (RAC1B) to enhance melanoma migration and invasion." (PMID 35954332, 2022). "To delineate a possible mechanism for the FOXD1-associated radioresistance in oral cancer, we next analyzed the mRNA levels of annotated genes on Illumina microarray after FOXD1 knockdown in A375 and MeWo melanoma cells by using GSE111766 dataset." (PMID 32967107, 2020). "Next, we transduced the four parental melanoma cell lines 624, 003, A375, and WM-266-4 with pQCXIP-FoxD1 (FoxD1-OX) or empty pQCXIP (Mock) that served as control." (PMID 29855470, 2018). "All four melanoma lines (FoxD1-OX or Mock) were transiently co-transfected with the luciferase construct and an additional pRL that served as internal control." (PMID 29855470, 2018). "In melanoma, overexpression of FOXD1 enhanced drug resistance of melanoma cells." (PMID 35607308, 2022). "We found that ectopic expression of FOXD1 accelerates melanoma onset (p = 3.33E−16, log-rank)." (PMID 35223844, 2022). "Although FOXD1 is extensively marked by H3K27me3 in melanocytes, we did not observe significant increases in FOXD1 expression in two in vivo melanoma models with PRC2 loss of function, possibly because the epigenetic programs that repress FOXD1 expression extend beyond H3K27me3." (PMID 35223844, 2022). "We showed that Forkhead Box superfamily member FOXD1 is required for melanoma progression since its silencing could significantly impair melanoma migration and invasion." (PMID 31118886, 2019). "FOXD1 also targets RAC1B to regulate melanoma cell motility." (PMID 31795213, 2019). "Importantly, FoxD1 expression was reduced following ADAR1 silencing in all four melanoma ADAR1-KD lines in the mRNA and protein levels." (PMID 29855470, 2018). "To test this hypothesis, we used miniCoopR to overexpress FOXD1 in melanoma." (PMID 35223844, 2022). "Indeed, overexpression of FoxD1 enhanced the expression of miR-22 in all four melanoma lines." (PMID 29855470, 2018). "We identified FOXD1 as a top target of PRC2 that is silenced in melanocytes and found that aberrant overexpression of FOXD1 accelerated melanoma onset." (PMID 35223844, 2022). "We identified FOXD1 as a PRC2 target that is marked by H3K27me3, silenced in melanocytes, and expressed minimally in zebrafish and mouse melanomas." (PMID 35223844, 2022).
melanoma (continued). "Complementary, in melanoma cancer, FOXD1 was critically involved in invasion and migration via indirect regulation of RAC1b and MMP-9 alternative splicing in melanoma cells." (PMID 34772357, 2021). "Along with FOXD1 and ATF3, CREB5 formed a transcription factor regulatory network that negatively regulates MAPK signalling, which is suppressed by FZD3 in melanoma." (PMID 32843066, 2020). "Indeed, statistically significant downregulation of ADAR1 and FoxD1, as well as upregulation of ITGB3, were observed congruently along human melanoma progression." (PMID 29855470, 2018). "Importantly, the expression of ADAR1 and FOXD1 decreased, while the expression of ITGB3 increased, along melanoma development." (PMID 29855470, 2018). "Because FOXD1 is not expressed in melanocytes and is minimally expressed in melanoma, we hypothesized that overexpression of FOXD1 would alter melanoma formation." (PMID 35223844, 2022).
lung cancer (11 papers, 2019 to 2024). A malignant neoplasm involving the lung. "In lung cancer cells, FOXD1 causes the transcriptional activation of Gal-3 by binding to its promoter, thus upregulating its expression and further promoting cell growth and motility." (PMID 37906341, 2023). "Consistently, we and others have shown that elevated FOXD1 protein expression can be detected in clinical lung cancer tissues and associated with tumor malignancy." (PMID 31795213, 2019). "Recently, clinical mRNA microarray data identified FOXD1 as a factor associated with poor prognosis and that is required for lung cancer cell proliferation." (PMID 31795213, 2019). "Moreover, lung cancer patients with high FOXD1 and Gal-3 gene expression were associated with a poor prognosis in a different database (LUAD-TCGA and Lung Meta-base)." (PMID 31795213, 2019). "Numerous studies had shown that FOXD1 was known to promote the malignant processes of various types of cancers, such as pancreatic cancer, gastric cancer, and lung cancer." (PMID 37701829, 2023). "In lung cancer, FOXD1 coupled with Gal-3 increased tumor growth and motility, whereas depletion of Gal-3 attenuated FOXD1-mediated tumorigenesis." (PMID 35607308, 2022). "For example, FOXD1 is overexpressed in lung cancer and activate galectin-3/LGALS3 expression to promote lung cancer aggressiveness." (PMID 34028536, 2021). "In this study, we demonstrated that FOXD1 promoted lung cancer aggressiveness by targeting Gal-3, which acts as an oncogene in lung cancer." (PMID 31795213, 2019). "Ectopic expression of FOXD1 increased the expression of Gal-3 and the growth and motility of lung cancer cells, whereas depletion of Gal-3 attenuated FOXD1-mediated tumorigenesis." (PMID 31795213, 2019). "We thus evaluated FOXD1 and Gal-3 gene expression in lung cancer patients from the SurvExpress database (LUAD-TCGA and Lung Meta-base) and found high FOXD1 and Gal-3 expression in the high-risk group." (PMID 31795213, 2019). "More importantly, we showed that the positive regulatory loop of activation of FOXD1 and Gal-3 increased the growth and motility of lung cancer." (PMID 31795213, 2019). "To evaluate the correlation between FOXD1 and Gal-3 in lung cancer tissues, we determined FOXD1 or Gal-3 expression by immunochemistry staining in human lung cancer tissue microarrays." (PMID 31795213, 2019). "The co-expression of FOXD1 and Gal-3 promoted, whereas the co-knockdown of both attenuated, lung cancer cell growth and motility in vitro." (PMID 31795213, 2019). "Ectopic or depleted expression further suggested that FOXD1 promotes the growth and motility of lung cancer cells." (PMID 31795213, 2019). "Overall, these data indicated that FOXD1 and Gal-3 form a positive relationship to promote tumor progression in human lung cancer tissues." (PMID 31795213, 2019). "The overexpression of both FOXD1 and Gal-3 form a positive regulatory loop to promote lung cancer aggressiveness." (PMID 31795213, 2019). "Based on microarray analysis, we identified galectin-3/LGALS3 (Gal-3) as a potential downstream target of FOXD1, as FOXD1 transactivated Gal-3 by interacting with the Gal-3 promoter to upregulate Gal-3 in FOXD1-overexpressing CL1-0 lung cancer cells." (PMID 31795213, 2019). "Here, we provide evidence that links FOXD1 with Gal-3 in lung cancer, in which FOXD1 enhanced Gal-3 expression; subsequently, Gal-3-mediated ITGβ1/ETS-1 signaling contributed to further increase FOXD1 expression." (PMID 31795213, 2019). "Abnormal expression of FOXD1 and Gal-3 is known to contribute to cancer pathogenesis, which makes them therapeutic targets for various cancers including lung cancer." (PMID 31795213, 2019). "Although several studies have tried to unravel the molecular networks of FOXD1, the molecular mechanisms related to FOXD1 remain largely unexamined, especially in lung cancer." (PMID 31795213, 2019).
lung cancer (continued). "FOXD1 was found to bind to the promoter region (−1075 to −1058 nt) of the Gal-3 gene in human lung cancer cells." (PMID 31795213, 2019). "Taken together, these findings suggest that ITGβ1/ERK signaling mediates the relationship between Gal-3 and FOXD1 in lung cancer." (PMID 31795213, 2019). "Similarly, FOXD1 and Gal-3 interact to form a positive feedback loop, which is a potential therapeutic target in lung cancer." (PMID 39494294, 2024). "In Sohei Nakayama's study, FOXD1 expression was only significantly associated with squamous carcinoma, but not with other lung cancer subtypes." (PMID 35607308, 2022). "Although FOXD1 is involved in the pathological development of lung cancer, especially in LUSC, the related functions of FOXD1 contributing to LUSC progress have remained largely unknown." (PMID 35607308, 2022). "FOXD1 and Gal-3 positively correlated with aggressiveness in human lung cancer." (PMID 31795213, 2019). "Moreover, FOXD1 combined with Gal-3 served as an independent prognostic factor for lung cancer patients." (PMID 31795213, 2019). "Furthermore, we observed that the overexpression of FOXD1 increased the proliferation and colony-forming ability of lung cancer cells, while the depletion of Gal-3 attenuated the phenotypes induced by FOXD1." (PMID 31795213, 2019). "Furthermore, using clinical human lung cancer tissue microarrays, we found that both FOXD1 and Gal-3 were positively correlated in advanced lung tumor tissues." (PMID 31795213, 2019). "Our findings demonstrate that this positive feedback loop between FOXD1 and Gal-3 might regulate lung cancer aggressiveness in an additive manner." (PMID 31795213, 2019). "Collectively, these data indicated that FOXD1 might promote lung cancer aggressiveness through the upregulation of Gal-3." (PMID 31795213, 2019). "FOXD1 and Gal-3 form a positive loop that promotes lung cancer aggressiveness." (PMID 31795213, 2019). "Moreover, both FOXD1 and Gal-3 were positively correlated in human lung cancer tissues." (PMID 31795213, 2019). "However, the downstream target involved in FOXD1 in lung cancer remains to be characterized." (PMID 31795213, 2019). "Our findings demonstrated that FOXD1 and Gal-3 form a positive feedback loop in lung cancer, and interference of this loop may serve as an effective therapeutic target for the treatment of lung cancers, particularly those related to dysregulation of Gal-3." (PMID 31795213, 2019). "This has been demonstrated by galectin-3 and the transcription factor FOXD1 forming a positive feedback loop through the ERK intracellular signaling pathway, which promotes lung cancer aggressiveness." (PMID 38927753, 2024).
pancreatic cancer (10 papers, 2019 to 2025). "High level of FOXD1 is associated with poor prognosis of pancreatic cancer and facilitates the proliferation, invasion, and metastasis of pancreatic cancer cells." (PMID 41214670, 2025). "Although FOXD1 has been found to be involved in the malignant processes of several types of cancers, its role in pancreatic cancer (PC) is not well understood." (PMID 36057597, 2022). "The FOXD1 expression in pancreatic cancer cell lines was verified much higher compared with the normal pancreatic duct epithelial cell line HPDE6-C7." (PMID 31602254, 2019). "By analyzing GSE16515 in the GEO database, FOXD1 expression in pancreatic cancer tissues was higher than those in normal paraneoplastic tissues (p<0.05)." (PMID 31602254, 2019). "Pancreatic cancer cells were treated with gemcitabine following FOXD1 knockdown, and the killing effect of gemcitabine increased significantly (p<0.05)." (PMID 31602254, 2019). "Based on the present study, it showed miR-30a-5p overexpression significantly enhanced the chemosensitivity of gemcitabine to pancreatic cancer cells by directly targeting FOXD1." (PMID 31602254, 2019). "In pancreatic cancer, FOXD1 contributes to cancer development by promoting SLC2A1 transcription." (PMID 40999468, 2025). "Although FOXD1 is overexpressed in pancreatic cancer cells and facilitates the progression of pancreatic cancers, the expression and physiological role of FOXD1 in β-cells remain unknown." (PMID 38092733, 2023). "Moreover, OIP5-AS1 facilitated the tumor malignant progression via targeting miR-429/FOXD1/ERK axis in pancreatic cancer." (PMID 35756672, 2022). "Also FOXD1 expression was detected by IHC and the expression of FOXD1 in the pancreatic cancer tissues was stronger than those in normal pancreatic tissues." (PMID 31602254, 2019). "Previous studies showed that activation of FOXD1 may induce the ERK signaling pathway and chemotherapeutic drug resistance 12,13, and we also confirmed that ERK signaling pathway was inhibited after FOXD1 knockdown in pancreatic cancer." (PMID 31602254, 2019). "Therefore, the overexpression of miR-30a-5p may increase the sensitivity of pancreatic cancer to gemcitabine by targeting FOXD1." (PMID 31602254, 2019). "Furthermore, FOXD1 is a direct target of miR-30a-5p and the miR-30a-5p/FOXD1/ERK axis may play an important role in the development of gemcitabine resistance in pancreatic cancer." (PMID 31602254, 2019). "Consistent with the previous finding, in the present study too, we elucidated that the miR-30a-5p/FOXD1 axis is one of the mechanisms that regulates the chemosensitivity of gemcitabine in PDAC, and interfering with miR-30a-5p/FOXD1 axis might be a therapeutic strategy for pancreatic cancer." (PMID 31602254, 2019). "FOXD1 accelerates aerobic glycolysis by increasing GLUT1 expression, ultimately promoting the malignant behaviors of pancreatic cancer cells." (PMID 41214670, 2025). "FOXD1 upregulates GLUT1 expression, thereby facilitating the proliferation, invasion, and metastasis of pancreatic cancer cells through the regulation of aerobic glycolysis." (PMID 38052785, 2023). "A recent report also suggested that FOXD1 enhances GLUT1 expression, leading to cell proliferation, invasion, and metastasis by modulating aerobic glycolysis in pancreatic cancer." (PMID 37234983, 2023). "FOXD1 is a direct target of miR-30a-5p, and the miR-30a-5p/FOXD1/ERK axis played an important role in the development of gemcitabine resistance in pancreatic cancer." (PMID 31602254, 2019). "Also, in pancreatic cancer, FOXD1 directly stimulates SLC2A1 transcription, suppresses SLC2A1 degradation via an RNA‐induced silencing complex, upregulates GLUT1 expression and ultimately facilitates the growth, invasion and metastasis of pancreatic cancer cells by controlling aerobic." (PMID 39661501, 2024).